GAA (alpha glucosidase)
Diseases named in the same sentence as GAA in open-access papers (continued):
Sharing a sentence is not in itself a finding about the gene and the disease.
diabetes (115 papers, 2009 to 2026). "The increasing prevalence of diabetes and the side effects associated with current medications necessitate the development of novel candidate drugs targeting alpha-glucosidase as a potential treatment option." (PMID 39241083, 2024). "Among them, we identified four pentacyclic triterpenes that displayed potent inhibitory activity against alpha-glucosidase, an enzyme associated with diabetes." (PMID 39065741, 2024). "The present study employed a systematic approach combining computational and analytical methods to identify potential drug candidates targeting alpha-glucosidase, a key enzyme implicated in metabolic disorders such as type 2 diabetes mellitus." (PMID 39241083, 2024). "Alpha glucosidase is a critical drug target implicated in the mechanisms of diabetes mellitus and its inhibition controls hyperglycemia." (PMID 35723349, 2022). "The alpha-glucosidase enzyme releases glucose into the bloodstream, causing hyperglycemia, which worsens diabetes patients’ symptoms and speeds up complications." (PMID 34832691, 2021). "We performed a systematic review and meta-analysis to evaluate the effect of alpha-glucosidase inhibitors (AGIs) on the risk of cancer in patients with diabetes mellitus." (PMID 29113364, 2017). "We know from the literature that there are risk factors and predisposing diseases associated with PI, such as diabetes and alpha-glucosidase inhibitor treatment, COPD and asthma, diseases affecting GI motilities and mucosal integrity such as inflammatory bowel disease." (PMID 35406436, 2022). "Likewise, the use of alpha-glucosidase inhibitors to treat type 2 diabetes mellitus has been found to be associated with PCI." (PMID 28241852, 2017). "An approach used in the treatment of diabetes mellitus is the inhibition of carbohydrate digesting enzymes, specifically alpha-glucosidase, in the gastrointestinal tract." (PMID 39949374, 2025). "These compounds help to regulate alpha-amylase, alpha-glucosidase, and insulin levels, making the plant effective for treating diabetes." (PMID 40365188, 2025). "For the control of hyperglycemia, acarbose was administered because in our previous experiments, we established good alpha-glucosidase inhibitory potential of Tanacetum balsamita, and an extract of this species was used in another in vivo diabetes study." (PMID 40699692, 2025). "Alpha-glucosidase inhibitors have been considered as the most effective agents in preventing hyperglycaemia and alternative targets for the treatment of Diabetes mellitus (DM)." (PMID 41186211, 2025). "To further target precursors required for glucuronidation we administered acarbose, an oral alpha-glucosidase inhibitor used in managing type 2 diabetes mellitus and previously shown to reduce glucose in Drosophila." (PMID 40634495, 2025). "Metformin, glimepiride alone or in combinations, teneligliptin, and alpha-glucosidase inhibitors like acarbose and voglibose were also commonly used for the treatment of diabetes in the current study." (PMID 38389602, 2024). "Many studies have searched for more effective and safe inhibitors of alpha-glucosidase and alpha-amylase from natural sources to develop nutraceuticals that can prevent and manage diabetes." (PMID 39275332, 2024). "The analysis of 81,197 triazole derivatives revealed that these nine compounds demonstrate potent inhibitory activity against alpha-glucosidase, a critical target in diabetes treatment." (PMID 39241083, 2024). "These compounds exhibit strong antioxidant activity, contributing to their ability to effectively inhibit key enzymes like alpha-amylase and alpha-glucosidase, pivotal in diabetes." (PMID 39204151, 2024). "Teneligliptin (n=28, 10.69%) and alpha-glucosidase inhibitors like acarbose and voglibose (n=31, 11.83%) were also commonly used for the treatment of diabetes in the elderly." (PMID 38389602, 2024).
diabetes (continued). "In a meta-analysis, thiazolidinedione (we studied pioglitazone), and alpha-glucosidase inhibitor (we looked at acarbose) were also found to be mortality neutral in patients with diabetes mellitus type 2 and COVID-1927." (PMID 38538694, 2024). "In a meta-analysis, a thiazolidinedione and an alpha-glucosidase inhibitor were also found to be mortality-neutral in patients with diabetes mellitus type 2 and COVID-19." (PMID 38536830, 2024). "Among the current strategies for treating diabetes, the inhibition of alpha-glucosidase is a key approach." (PMID 39241083, 2024). "This study is focused on creating new compounds that exhibit a strong inhibition of alpha-glucosidase, which is a pivotal enzyme in diabetes control." (PMID 38399476, 2024). "PI caused by chemotherapeutic agents, monoclonal antibody drugs, and alpha-glucosidase inhibitors for diabetes were treated successfully with therapy discontinuation in 96 cases (11.7%)." (PMID 38392601, 2024). "The discovery of alpha-glucosidase inhibitors in natural sources has led to the production of safe and easily manufactured drugs replacing previous diabetes medications such as miglitol, voglibose, and acarbose." (PMID 36865035, 2023). "The alkaloid 1-(DNJ) extracted from mulberry leaves is currently known as a good inhibitor of alpha-glucosidase for the treatment of diabetes, and it also has the ability to improve insulin resistance in this way to synergistically control diabetes." (PMID 37089923, 2023). "This compound has been reported to exert inhibitory effects in vitro against alpha-amylase and alpha-glucosidase enzymes and thereby plays a vital role in treating diabetes." (PMID 36583135, 2023). "Z. majdae also shows inhibitory activity against alpha-glucosidase and alpha-amylase enzymes, making it a possible candidate for diabetes treatment." (PMID 36865035, 2023). "Molecular docking results identified four and/or five best compounds against each target enzyme (alpha-glucosidase, dipeptidyl peptidase-IV, aldose reductase, and protein tyrosine phosphatase-1B (PTP-1B)) implicated in diabetes." (PMID 37969920, 2023). "By decelerating the conversion of carbohydrates into simple sugars, alpha-glucosidase suppressants can reduce post-meal glucose increases, facilitating in maintaining of steady blood sugar levels and functioning as an effective diabetes treatment." (PMID 38002116, 2023). "According to the study, Z. majdae extracts have inhibitory effects (50% and higher) on the alpha-glucosidase enzyme, making them a viable candidate for diabetes treatment." (PMID 36865035, 2023). "It has been demonstrated that many natural 14-OH taxoids act as effective alpha-glucosidase inhibitors and are useful in the treatment of diabetes." (PMID 36903424, 2023). "This study aimed to compare the effects of an SGLT2 inhibitor with an alpha-glucosidase inhibitor on atherogenic risk factors, including high-risk lipid profile and inflammatory markers related to the incidence of ASCVD in diabetes patients with heart failure." (PMID 36104378, 2022). "Postprandial hyperglycemia in type 2 diabetes mellitus patients can be controlled by inhibiting metabolic carbohydrate digesting enzymes such as alpha-amylase, alpha-glucosidase, and dipeptide peptidase IV19." (PMID 36460661, 2022). "A literature search was performed in PubMed, Google Scholar, WorldCat, and the Directory of Open-Access Journals (DOAJ) by using the keywords “pneumatosis intestinalis”, “alpha-glucosidase inhibitors”, and “diabetes”." (PMID 36233785, 2022). "We assembled a retrospective cohort of type 2 diabetes mellitus (T2DM) patients who were new users of TZDs or alpha glucosidase inhibitors (AGIs) using the Yinzhou Regional Health Care Database." (PMID 36271052, 2022). "The current pharmacotherapy for diabetes involves insulin secretagogues, insulin sensitizers, alpha-glucosidase inhibitors, biguanides, incretin mimetics, sodium-glucose co-transport-2 inhibitors, amylin antagonists, and insulin." (PMID 36545334, 2022).
diabetes (continued). "Compared to BDC-0, BDC-3/4 were older, had a longer history of diabetes, and were more likely to take insulin injections, alpha-glucosidase inhibitors, and medications for hypercholesterolemia and hypertension." (PMID 36387868, 2022). "Since plant extracts from Calotropis procera have been extensively used in the treatment of diabetes mellitus, the present study used molecular docking and dynamics simulation techniques to screen its constituents against the receptor alpha glucosidase." (PMID 35723349, 2022). "Among the various ingredients, 1-DNJ is recognized for its ability to combat diabetes by primarily working as an alpha-glucosidase inhibitor." (PMID 36295064, 2022). "Alpha-glucosidase regulates postprandial hyperglycemia and is considered to be a potential therapeutic target for diabetes treatment." (PMID 35308202, 2022). "Alpha-glucosidase is one target enzyme for reduce glucose level in the management of type 2 diabetes mellitus." (PMID 35163903, 2022). "Alpha-glucosidase inhibitors, including voglibose, are used to treat diabetes; they lower glucose levels and reversibly inhibit the absorption of complex carbohydrates." (PMID 36104378, 2022). "We conducted this study to investigate the liver-related long term outcomes of alpha-glucosidase inhibitors (AGIs) in patients with diabetes and cirrhosis." (PMID 36618937, 2022). "Several alpha-glucosidase inhibitor drugs (such as Miglitor Acarbose, and Voglibose) are used in the treatment of diabetes." (PMID 34685875, 2021). "Different medicines have showed effectiveness against diabetes mellitus including glibenclamide, metformin, and alpha-glucosidase inhibitors." (PMID 33752586, 2021). "Participants with ΔFMD < 10% had significantly more patients with diabetes and hypoglycemic therapy (biguanides, sulfonylureas, glinides and alpha-glucosidase inhibitors) than those with ΔFMD ≥10%." (PMID 32000667, 2020). "Alpha-glucosidase inhibitors are standard drugs for treating diabetes; they also exhibit the potential to act against HBV2–5." (PMID 31913341, 2020). "Alpha-glucosidase inhibitors (AGIs) such as acarbose, miglitol and voglibose are oral drugs used in the management of diabetes, primarily to reduce post-prandial glucose concentrations." (PMID 31623625, 2019). "Other prior concomitant diabetes medications were used by few subjects overall (thiazolidinediones 2.8%, alpha glucosidase inhibitors 0.1%)." (PMID 30252913, 2018). "Pseudotetrasaccharide acarbose, with brand name Precose, has been employed as an alpha-glucosidase inhibitor for managing diabetes mellitus type 2." (PMID 29348771, 2017). "As can be seen, alpha-glucosidase inhibitors were used in the treatment of patients with diabetes mellitus type 2 due to reduction of the impact of carbohydrates on blood sugar." (PMID 29348771, 2017). "The alpha-glucosidase inhibitor acarbose has been shown to decrease incident diabetes in people with impaired glucose tolerance individuals and decrease cardiovascular events." (PMID 26818604, 2016). "The launch of new medications, alpha-glucosidase inhibitors and thiazolidinediones, provided physicians and patients more choices for diabetes management." (PMID 25949816, 2015). "Alpha-glucosidase inhibitors currently form an important basis for developing novel drugs for diabetes treatment." (PMID 25658100, 2015). "One of the effective therapeutic approaches in the treatment of diabetes mellitus is decreasing the postprandial hyperglycemia through the inhibition of alpha glucosidase." (PMID 25396726, 2014). "As a result of this unique mechanism, alpha-glucosidase is effective for patients even if they have a comparatively long duration of diabetes and a severe deterioration of insulin secretion." (PMID 24684803, 2014). "We suggest that patients who are taking an alpha-glucosidase inhibitor for diabetes should discontinue use of that particular medicine prior to beginning radiotherapy." (PMID 24886457, 2014).
diabetes (continued). "The effect is more pronounced for CM as compared to acarbose which is currently the most widely used alpha glucosidase inhibitor for treatment of diabetes." (PMID 21792369, 2012). "SE50/110 is known as the wild type producer of the alpha-glucosidase inhibitor acarbose, a potent drug used worldwide in the treatment of type-2 diabetes mellitus." (PMID 22443545, 2012). "Acarbose is an oral alpha-glucosidase and alpha-amylase inhibitor that was first launched by Bayer in Switzerland in 1989 for the oral treatment of type-2 diabetes mellitus." (PMID 22104600, 2011). "Voglibose is an alpha-glucosidase inhibitor used for lowering post-prandial blood glucose levels in people with diabetes mellitus." (PMID 22104600, 2011). "Five types of classical oral antihperglycemic drugs are currently approved for the treatment of diabetes: biguanides, sulfonylureas, meglitinides, glitazones and alpha-glucosidase inhibitors." (PMID 19619327, 2009). "Similarly, alpha-glucosidase inhibitors are widely used in diabetes management due to their ability to delay carbohydrate digestion and absorption in the intestine, thereby reducing postprandial blood glucose spikes." (PMID 40238298, 2025). "Luteolin helps fight diabetes via inhibition of alpha‐glucosidase and ChE activity." (PMID 39830909, 2025). "Furthermore, the ethanolic extract of MFSs yielded compounds with promising hypoglycemic potential in vitro against digestive enzymes such as alpha-amylase and alpha-glucosidase—key targets in diabetes management." (PMID 40805672, 2025). "Regarding concomitant drug use for diabetes, alpha-glucosidase inhibitors, dipeptidyl peptidase-4 inhibitors, glinides, glucagon-like peptide-1 agonists, and insulin were more commonly used as the albuminuria severity increased, while biguanides were less frequently used." (PMID 37955878, 2024). "Based on the findings, it can be concluded that the bioactive secondary metabolites present in PK have the potential to treat diabetes and dyslipidemia through various mechanisms, such as increasing insulin secretion, inhibiting intestinal alpha-glucosidase, and activating glucokinase." (PMID 39334723, 2024). "Finally, CLAE can act as a strong alpha glucosidase inhibitor and can thus be used for the management of diabetes mellitus." (PMID 39598662, 2024). "Research has demonstrated that kaempferol may interact with some amino acid residues within the active site of alpha-glucosidase, thereby achieving the purpose of treating diabetes." (PMID 39221164, 2024). "In terms of the concomitant diseases, 40 patients (20.83%) had a history of polypectomy or abdominal surgery, 11 patients (5.73%) were with respiratory diseases, 16 patients (8.33%) had diabetes mellitus, and 9 cases (4.69%) of them received alpha-glucosidase inhibitor (α-GI) therapy." (PMID 37823317, 2023). "In addition to their utility in the treatment of diabetes, alpha-glucosidase inhibitors have attracted attention for their therapeutic potential in treating a variety of diseases." (PMID 38002116, 2023). "Alpha-amylase and alpha-glucosidase inhibitors are important in the treatment of diabetes." (PMID 36865035, 2023). "alpha-glucosidase inhibitors may be useful for the management of diabetes in patients with compensated liver cirrhosis." (PMID 36618937, 2022). "Acarbose, an alpha-glucosidase inhibitor that inhibits the digestion of carbohydrate in the intestine, is commonly used to treat diabetes in Asian populations, probably because of its glucose lowering effect for patients who consume Asian diets that have a high content of carbohydrate." (PMID 32489710, 2020). "The specific action of cumin may be due to the presence of cuminaldehyde which inhibits aldose reductase and alpha-glucosidase, as two enzymes which can help diabetes progression." (PMID 28357199, 2016). "He suffered from diabetes mellitus and took an alpha-glucosidase inhibitor." (PMID 24886457, 2014).
diabetes (continued). "The role of alpha glucosidase in diabetes has been discussed previously at AC2." (PMID 25396726, 2014). "Thus CM can generate better lead molecule as alpha glucosidase inhibitor for treatment of diabetes mellitus particularly in control of postprandial glucose level." (PMID 21792369, 2012). "The Acarbose Cardiovascular Evaluation (ACE) trial (ISRCTN91899513) evaluated the alpha‐glucosidase inhibitor acarbose, compared with placebo, in 6522 patients with coronary heart disease and impaired glucose tolerance in China and showed a reduced incidence of diabetes." (PMID 37915263, 2024). "Thus, inhibition of alpha glucosidase can be used as an ideal method to prevent diabetes." (PMID 34604273, 2021). "Alpha-amylase and alpha-glucosidase enzyme inhibition is an effective and rational approach for controlling postprandial hyperglycemia in type II diabetes mellitus (DM)." (PMID 35432813, 2021). "However, multiple adverse effects like abdominal cramps or diarrhea could reduce patient adherence to treatment, therefore natural products with alpha glucosidase inhibitory effect may become successful drug candidates for the management of diabetes mellitus." (PMID 33925692, 2021). "The findings suggest that these compounds might possibly become prominent natural candidates to inhibit alpha-glucosidase and alpha-amylase as well as oxidative stress related to diabetes with the prospect to be used in the formulation of diabetes drugs upon further biological studies." (PMID 33228164, 2020). "Indeed, novel drugs that may exert inhibitory effects on alpha glucosidase and cholinesterase are being developed for the treatment of both type 2 diabetes mellitus and AD." (PMID 32489710, 2020). "Acarbose is an alpha-glucosidase inhibitor (AGI) that has been approved for the treatment of type 2 diabetes mellitus (DM)." (PMID 24886457, 2014). "The major conventional hypoglycemic drugs used for the treatment of diabetes include diguanides, sulphonylureas, SGLT2 inhibitors, DPP-4 inhibitors, GLP-1 receptor agonists, alpha glucosidase inhibitors, and thiazolidinediones (TZDs), etc.." (PMID 38179301, 2023). "These were the UK Prospective Diabetes Study (UKPDS), STOP-NIDDM, the Alpha-glucosidase-inhibitor Blocks Cardiac Events in Patients with Myocardial Infarction and Impaired Glucose Tolerance (ABC) trial, and the ACE trial." (PMID 31623625, 2019). "The ethanolic extract of A. paniculata and AGL showed an alpha-glucosidase inhibitory effect in a concentration-dependent manner (IC50 = 11.0 to 50.9 mg/mL), suggesting a potential candidate for the management of type 2 diabetes mellitus." (PMID 28878680, 2017). "Classical non-insulin antihyperglycemic drugs currently approved for the treatment of type 2 diabetes mellitus (T2DM) comprise five groups: biguanides, sulfonylureas, meglitinides, glitazones and alpha-glucosidase inhibitors." (PMID 19619327, 2009). "In relation to diabetes, NLE has been reported to have insulin secretagogue, PPARgamma antagonistic, and alpha-glucosidase inhibiting properties and may help improve glycemic control." (PMID 37305057, 2023). "Taken together, these findings, suggest that the single ingestion of GvEx or Guava Leaf Tea can reduce postprandial glucose elevation via the inhibition of alpha-glucosidase in mice and human subjects with or without diabetes." (PMID 20181067, 2010). "For the alpha-glucosidase inhibitors, meglitinides, non-sulfonylureas, and sulfonylureas, perhaps because the FAERS database had more reports than the JADER database or the association of diabetes mellitus with BP." (PMID 33850463, 2021). "On the other hand, we don’t know whether anti-diabetic agents, such as metformin and alpha-glucosidase inhibitors, can be used in patients without diabetes and whether anti-diabetic agents not leading to hypoglycemia are still beneficial in such conditions." (PMID 33720996, 2021).